SNORD15A (small nucleolar RNA, C/D box 15A)
Synonyms: U15A; RNU15A; SNORNA
Gene: Small nucleolar RNA gene on chromosome 11 (75,400,391 to 75,400,538, forward strand). Ensembl gene ENSG00000206941.
Gene Ontology:
Biological process: RNA processing
Cellular component: nucleolus
Homologues: Orthologues: chimpanzee SNORD15 (100% identical), macaque SNORD15 (94% identical), pig SNORD15 (87% identical), rat Snord15a (81% identical), mouse Snord15a (80% identical), rabbit SNORD15A (79% identical), dog SNORD15 (78% identical), tropical clawed frog SNORD15 (61% identical), guinea pig SNORD15 (58% identical), guinea pig SNORD15 (46% identical). Paralogues in human: SNORD15B (61% identical).
Diseases named in the same sentence as SNORD15A in open-access papers:
SNORD15A is named in the same sentence as 1 disease in open-access papers, as found by Europe PMC text mining. Sharing a sentence is not in itself a finding about the gene and the disease.
SNORD15A shares sentences with these, for which no sentence is quoted: cancer (2 papers).